CDH11 (cadherin 11)
Diseases named in the same sentence as CDH11 in open-access papers (continued):
Sharing a sentence is not in itself a finding about the gene and the disease.
breast carcinoma (continued). "Although some studies reported that CDH11 is frequently methylated and silenced in certain types of cancers, cumulative emerging evidence suggests that CDH11 may play a critical role in promoting tumorigenesis and metastasis in breast cancer." (PMID 37558205, 2023). "In addition to PDAC, increased Cdh11 expression was observed in many other cancers including breast cancer, stomach and colon cancer." (PMID 37954069, 2023). "Interestingly, β‐catenin remained bound to carboxy‐terminal fragments (CTFs) of CDH11, the products of CDH11 cleavage, and co‐localized with CTFs in the nucleus in the majority of breast cancer samples." (PMID 37558205, 2023). "For example, human and murine breast cancer-secreted EVs enriched in cadherin 11 (CDH11) and α5 integrin delivered runt-related transcription factor 2 (RUNX2) to the bone, inducing an osteogenic environment and bone lesions that promoted bone colonization by cancer cells." (PMID 37350937, 2023). "Particularly, breast cancer is one of the cancer types with high CDH11 expression." (PMID 37558205, 2023). "Our discovery provides mechanistic insight into the role of CDH11 in tumorigenesis and metastasis and offers a plausible explanation of the clinical data correlating tumor grade and metastatic potential with the levels of CDH11 expression in breast cancer cells." (PMID 37558205, 2023). "Breast cancer cells with high runt-related transcription factor 2 (RUNX2) expression could secrete EVs with high levels of cadherin 11 (CDH11) and integrin α5 (ITGA5), which synergistically promote osteogenic PMN formation." (PMID 36430471, 2022). "In breast cancer, CDH11 can only be expressed in cells and specimens of invasive breast cancer 30, while peripheral CDH11 expression enhances the migration and metastasis of breast cancer cells, indicating that CDH11 plays a key part in the development of breast cancer 31,32." (PMID 33442417, 2021). "Based on the analysis of large data of breast cancer, it was found that the expression of CDH11 was positively correlated with the expression of Wnt signal components such as β-catenin, Wnt2 and TCF2, and the expression of CDH11 and β-catenin in TNBC tissues was high at the same time." (PMID 33442417, 2021). "In breast cancer cells, up regulation or overexpression of CDH11 may lead to increased bone metastasis in breast cancer." (PMID 33442417, 2021). "In addition, in women with primary tumors smaller than 2 cm without lymph node metastasis, the presence of CAF-S1 cells favors breast cancer metastasis to the bone via CDH11/osteoblast cadherin." (PMID 33922795, 2021). "Recently, it was suggested that CDH11 acts as a tumor suppressor gene as demonstrated by its methylated and silenced status in malignant tissues such as in the nasopharyngeal, esophageal, gastric, hepatocellular carcinoma, colon, and breast carcinoma." (PMID 30691241, 2019). "Inhibition of CDH11 in breast cancer cell lines reduced migration and invasion ability, suggesting that it may play an important role in TNBC metastasis." (PMID 30691241, 2019). "The 231/LM2-4 cell line was selected, as indicated, from the well characterized MDA-MB-231 human breast cancer cell line, which apart from the typical expression profile of triple negative tumors, expresses c-Met, cadherin-11 (similar to N-cadherin) and a mutant form of p-53." (PMID 31536574, 2019). "Lastly, we showed that CDH11, ILF3 and HOXC8 were expressed at statistically higher levels in breast cancer specimens than in normal breast tissues, and the association of CDH11, ILF3 and HOXC8 was linked to poor distant metastasis-free survival for breast cancer patients." (PMID 29296180, 2017). "In breast cancer, CDH11 is expressed only in invasive cell lines and aggressive clinical specimens, and ectopically expressing CDH11 enhances the migration and metastasis of breast cancer cells, suggesting that CDH11 plays an important role in breast cancer progression and metastasis." (PMID 29296180, 2017).
breast carcinoma (continued). "The importance of CDH11 in breast cancer progression and metastasis is well established." (PMID 29296180, 2017). "Moreover, immunohistochemical staining of breast cancer specimens and normal breast samples showed that the expression of CDH11, ILF3 or HOXC8 was upregulated in breast cancer specimens." (PMID 29296180, 2017). "Moreover, we found that ILF3 increased proliferation and migration of breast cancer cells by facilitating CDH11 expression." (PMID 29296180, 2017). "Importantly, the expression levels of CDH11, ILF3 and HOXC8 are elevated in the advanced stages of breast cancer, and high expression of CDH11, ILF3 and HOXC8 is associated with poor distant metastasis-free survival (DMFS) for breast cancer patients." (PMID 29296180, 2017). "To further clarify the roles of HOXC8 in regulation of CDH11 transcription in breast cancer cells, we immunoprecipitated HOXC8 protein complexes and observed that interleukin enhancer-binding factor 3 (ILF3) co-precipitated with the HOXC8 protein in this study." (PMID 29296180, 2017). "In this study, we showed that knockdown of ILF3 significantly inhibited proliferation and migration of breast cancer cells, which could be rescued by ecto-expression of CDH11 in ILF3 knockdown cells." (PMID 29296180, 2017). "CDH11 selectively promotes bone metastatic homing and colonizatione of breast cancer cells and induces osteoclastogenesis through mediating interactions between breast cancer cells and marrow stromal/osteoblastic cells." (PMID 27806311, 2016). "Based on these findings, we hypothesize that HOXC8 regulates various genes transcription in breast cancer development, which includes activating cadherin-11 and inhibiting embigin transcription in breast cancer cells." (PMID 26090721, 2015). "As laboratory study may not always recapitulate clinical breast malignancy, we explored the potential clinical relevance of HOXC8/CDH11 expression in human breast cancer." (PMID 24810778, 2014). "Depletion of HOXC8 leads to the decrease in anchorage-independent cell growth, cell migration/invasion and spontaneous metastasis of breast cancer cells; however, suppressed tumorigenic events were fully rescued by ectopic CDH11 expression in HOXC8-knockdown cells." (PMID 24810778, 2014). "Given the importance of CDH11 in breast cancer cell migration and metastasis, we speculated that HOXC8 might impact breast tumorigenesis by serving as a CDH11 transcription factor." (PMID 24810778, 2014). "All CDH11 positive cell lines are in the basal B subset of poor prognosis breast cancer cells." (PMID 24681547, 2014). "Breast cancer patients may also shed CDH11 and/or CDH11-expressing cells into the circulation, which could potentially be utilized as a biomarker and/or companion diagnostic." (PMID 24681547, 2014). "To understand how CDH11 is involved in breast cancer cell migration, we previously showed that CDH11 was able to promote small GTPase Rac activity by facilitating the plasma translocation of Rac-specific GEF Trio, an event essential for Rac activation and cell migration in breast cancer cells." (PMID 24810778, 2014). "We show that CDH11 is increased early in breast cancer and ductal carcinoma in-situ." (PMID 24681547, 2014). "Additionally, CDH11 is frequently methylated in certain types of tumors, and it was reported that YTHDF1 translationally promoted CDH11 expression by recognizing m6A‐enriched sites of its transcript, thus promoting the osteolytic bone metastasis of breast cancer." (PMID 40387410, 2025). "Kaplan-Meier survival analyses showed that both high CDH11 and ILF3 were significantly associated with a poor distant metastasis-free survival (DMSF) rate for breast cancer patients (P = 0.014 and 0.023, respectively), and high expression of HOXC8 may also be associated with poor DMSF (P = 0.064)." (PMID 29296180, 2017).
breast carcinoma (continued). "Therefore, defining the regulatory mechanisms of CDH11 expression may unveil more effective therapeutic strategies to control breast cancer progression and metastasis." (PMID 29296180, 2017). "Since CDH11 is expressed only in invasive breast cancer cells and HOXC8 acts as either a transcriptional activator or repressor, we speculated that HOXC8 associated with other proteins to activate CDH11 transcription in breast cancer cells." (PMID 29296180, 2017). "Moreover, the findings that both high HOXC8 and CDH11 expression correlate with poor recurrence-free survival of breast cancer patients further support the notion that the HOXC8-CDH11 functional axis plays a critical role in breast tumor progression and metastasis." (PMID 24810778, 2014). "In breast cancer cells, FDA-approved potassium blocker amiodarone decreased the migration capacity in vitro, and metastasis and tumor growth in vivo through Cadherin-11." (PMID 37529110, 2023). "Cdh11 has previously been shown to be associated with EMT in cancer and antibody targeting of CDH11 inhibited EMT and suppressed metastasis in breast cancer." (PMID 37954069, 2023). "In this study, we demonstrated that CDH11 transcription required the formation of a protein complex containing the HOXC8, NF90 and NF110 proteins in breast cancer cells." (PMID 29296180, 2017). "Overall, these results indicated that CDH11, ILF3 and HOXC8 were highly upregulated in the advanced stages of breast cancer, and high expression of CDH11, ILF3 and HOXC8 were associated with a poor DMSF for breast cancer patients." (PMID 29296180, 2017). "It has been demonstrated that CDH11 promotes breast tumorigenesis, so we examined the effects of ILF3 on proliferation and migration of breast cancer cells." (PMID 29296180, 2017). "Recently, it has been demonstrated that miR-675 have several targets in different cancers, such as c-Cbl and Cbl-b in breast cancer, GPR55 in lung carcinoma, Rb in colorectal cancer, CALN1 in gastric cancer, Cadherin 11 in melasma." (PMID 27120794, 2016). "In our previous study, we showed evidences that HOXC8 functions as transcription activator to induce cadherin-11 expression in breast cancer cells, which suggested that HOXC8 may associate with different co-factors to activate or inhibit its target genes transcription in breast cancer cells." (PMID 26090721, 2015). "To further define the role of HOXC8 in CDH11 expression, we ectopically expressed HOXC8 in breast cancer MDA-MB-231 and Hs578T cell lines." (PMID 24810778, 2014). "Silencing of CDH11 or ITGA5 in breast cancer patients with ER/PR negative breast cancer cells recapitulated inhibitory effects of miRNA30 on skeletal tumor burden." (PMID 39742357, 2024). "Additionally, CDH11 can promote small GTPase Rac activity by facilitating the plasma translocation of the Rac-specific GEF Trio, which promotes breast cancer cell migration." (PMID 33391403, 2021). "Particularly, the negative association between the genes CDH2, CDH3, CDH11, CDH13, CDH18 and NAT1 N-acetylation activity supports observations of high NAT1 expression in breast cancer and increased metastasis." (PMID 35046826, 2021). "In contrast, epithelial expression of CDH11 was not different between cases and controls, while CDH11 was shown to be overexpressed in basal-like breast cancer." (PMID 32665033, 2020). "Thus, we posit that the high expression of CDH11 in patients with BL breast cancer and TNBC indicates that CDH11 plays an important role in these breast cancer molecular subtypes as an oncogene." (PMID 30691241, 2019). "Higher CDH11 mRNA expression level has been shown in malignant breast tumor than in non-malignant breast tumor or normal breast tissues." (PMID 30691241, 2019). "Furthermore, depletion of ILF3 by siRNA knockdown led to significant downregulation of CDH11 expression, suggesting that ILF3 was involved in regulating CDH11 expression in breast cancer cells." (PMID 29296180, 2017).
breast carcinoma (continued). "Moreover, immunohistochemistry (IHC) shows that expression of CDH11, ILF3 and HOXC8 are all upregulated in breast cancer specimens compared to normal breast tissues." (PMID 29296180, 2017). "Online analyses using cBioPortal showed that expression of CDH11, ILF3 or HOXC8 was elevated in the advanced stages of breast cancer, where high mRNA expression levels of CDH11 or HOXC8 were detected in cancer stage IV, and high mRNA expression levels of ILF3 were detected in cancer stage IIIC." (PMID 29296180, 2017). "Moreover, expression of CDH11, ILF3 and HOXC8 showed a significant tendency toward co-occurrence among these breast cancer samples." (PMID 29296180, 2017). "As a laboratory study may not always recapitulate the clinical malignancy, we performed immunohistochemistry staining (IHC) to examine CDH11, ILF3 and HOXC8 protein levels in breast cancer specimens and normal breast tissues." (PMID 29296180, 2017). "MDA-MB-231 CDH11-expressing breast cancer cells were inoculated into nude mice and treated MatrigelTM with a function-blocking monoclonal CDH11-specific antibody that does not exhibit significant side-effects in inflammatory RA, or control IgG." (PMID 24681547, 2014). "In addition to breast cancer and DCIS, CDH11 was increased in most data sets from brain and central nervous system (CNS), and gastrointestinal malignancies." (PMID 24681547, 2014). "In this study we use breast cancer cells with low levels of endogenous activated GSK-3 and β-catenin and prostate cancer cells with constitutively activated GSK-3 and β-catenin to show that, GSK3β regulates cadherin-11 expression in two ways." (PMID 19274078, 2009). "Three members of the miR-196 family where the resulting miR-196a-3p belongs – miR-196a-1, miR-196a-2, and miR-196b – could suppress breast cancer cell migration and metastasis by inhibiting HOXC8, which promotes tumorigenesis by regulating the expression of cadherin-11 in breast cancer." (PMID 34512726, 2021). "However, CDH11 role in canonical WNT signalling and CSCs in breast cancer is poorly understood." (PMID 30691241, 2019). "Moreover, we previously reported that CDH11 was able to promote endogenous Rac activity by assisting the membrane localization of Rac-specific GEF Trio, an event important for Rac activation and breast cancer cell migration." (PMID 24810778, 2014). "To functionally link HOXC8 to CDH11 in breast tumorigenesis, we show that the depletion of HOXC8 leads to the significant reduction in anchorage-independent cell growth, cell migration/invasion and spontaneous metastasis of breast cancer MDA-MB-231 and Hs578T cells." (PMID 24810778, 2014). "CDH11 is expressed in highly invasive but not in noninvasive breast cancer cell lines." (PMID 16083501, 2005). "Consequently, although our data demonstrates that stromal CDH11 is not exclusively responsible for changes in tumor growth at least in breast cancer, CDH11 expressing cells in the stroma almost certainly contribute to tumorigenesis, perhaps even in CDH11-negative tumors." (PMID 24681547, 2014). "However, how the expression of CDH11 is regulated in breast cancer cells is not understood." (PMID 24810778, 2014). "In breast cancer specimens, more than half of the cases exhibited strong and moderate positivity for CDH11, ILF3 or HOXC8, and only a few cases were negative for CDH11, ILF3 or HOXC8 (7.9% for CDH11, 13.2% for ILF3, and 13.2% for HOXC8)." (PMID 29296180, 2017). "Celecoxib and DMC inhibit the growth of CDH11 positive MDA-MB-231, BT549 and Hs578T basal-like breast cancer cells with EC50s in the 1-5 micromolar range but did not affect CDH11 negative MCF7 cells up to 40 micromolar." (PMID 24681547, 2014).
prostate carcinoma (28 papers, 2009 to 2025). A carcinoma that arises from epithelial cells of the prostate gland. "For example, increased cadherin-11 expression is associated with metastasis of prostate cancer to the bone, while promoter CpG methylation and silencing of the CDH11 gene in hepatocellular carcinoma (HCC) and other tumor types is associated with tumor-supporting cell properties." (PMID 37381005, 2023). "Previously, it was reported that CDH11 neutralizing antibodies slowed tumor growth and colony formation in breast, glioblastoma, and prostate cancer cells." (PMID 41263259, 2025). "In contrast, disruption of homotypic CDH11 interactions by an antibody targeting amino acids 343–348 on the CDH11 extracellular EC3 domain reduced the metastatic potential of prostate cancer to bone in a mouse model." (PMID 37558205, 2023). "Osteoblast cadherin (CDH11) was also shown to be an important stromal interaction protein in the osteoblastic metastasis in prostate cancer." (PMID 35685372, 2022). "Loss of E-cadherin and increased expression of N-cadherin and CDH11 in the human prostate cancer cells is able to change the invasive capacity and metastasis of the cells." (PMID 32600462, 2020). "This is also corroborated by a previous study demonstrating that anti-CDH11 antibody effectively suppressed bone metastasis in prostate cancer mouse model." (PMID 31248373, 2019). "The results were similar to previous studies that expression of cadherin-11 enabled prostate cancer (PCa) cells to intercalate into osteoblasts and increased the migration and invasion of PCa cells." (PMID 30839692, 2018). "For example, CDH11 expression promotes the formation of skeletal metastases in models of prostate cancer and can regulate glioma survival and migration." (PMID 24681547, 2014). "CDH11 knockdown in PC3 prostate cancer cells also resulted in reduced growth, but fell short of significance." (PMID 24681547, 2014). "In prostate cancer, it has been suggested that downregulation of CDH11 leads to inhibition of tumor cell migration in vivo and in vitro." (PMID 22200787, 2012). "Cadherin-11 promotes bone metastasis in a mouse model and its expression increases as the tumour progresses from primary prostate cancer to metastatic disease in lymph nodes and especially in bone." (PMID 21206493, 2011). "Our data show that the activity of the cadherin-11 3′-UTR is regulated by β-catenin in cells which normally express activated β-catenin such as PC-3 prostate cancer cells." (PMID 19274078, 2009). "Similarly, up‐regulation of CDH11 enhances cell motility and promotes metastasis of renal cell carcinoma and prostate cancer cells to bone." (PMID 37558205, 2023). "Up‐regulation of CDH11 also promoted advanced prostate cancer metastasis to bone." (PMID 37558205, 2023). "Interestingly, the increased expression of CDH11 can stimulate the invasion of some types of tumor cells (e.g., prostate cancer cells) and reduce the proliferation rate and ability to invade for other types of tumors (e.g., head and neck tumors)." (PMID 34149804, 2021). "Although the CellSearch® system appears to be the method of choice in prostate cancer, more specific markers may be necessary, such as cadherin-11, which is expressed not only on prostate cells and osteoblasts but also on prostate cancer cells exhibiting EMT." (PMID 26322014, 2015). "Indeed, significant reduction of growth and cell migration occurred upon CDH11 knockdown in PC3 prostate cancer cells." (PMID 24681547, 2014). "CDH11 knockdown and antibodies effective in RA slowed the growth of basal-like breast tumors and decreased proliferation and colony formation of breast, glioblastoma and prostate cancer cells." (PMID 24681547, 2014). "Both N-cadherin and cadherin-11 are overexpressed in osteoblasts and prostate cancer cells and are considered to have an important role in bone metastasis of prostate cancer." (PMID 21206493, 2011).